MKKS (MKKS centrosomal shuttling protein)
Description:
Probable molecular chaperone that assists the folding of proteins upon ATP hydrolysis. Plays a role in the assembly of BBSome, a complex involved in ciliogenesis regulating transports vesicles to the cilia. May play a role in protein processing in limb, cardiac and reproductive system development. May play a role in cytokinesis.
Synonyms: BBS6; HMCS; KMS; MKS
Tractability: PROTAC: ubiquitination databases record sites on it; its protein half-life has been measured.
Gene: Protein-coding gene on chromosome 20 (10,401,009 to 10,434,222, reverse strand). Ensembl gene ENSG00000125863.
Subcellular location: Cytoplasm, cytoskeleton, microtubule organizing center, centrosome; Cytoplasm, cytosol; Nucleus
Subcellular location (Human Protein Atlas): Basal body; Centrosome
Pathways (Reactome):
Organelle biogenesis and maintenance: BBSome-mediated cargo-targeting to cilium
Gene Ontology:
Molecular function: protein binding; RNA polymerase II-specific DNA-binding transcription factor binding; ATP binding
Biological process: cilium assembly; brain morphogenesis; cerebral cortex development; chaperone-mediated protein complex assembly; convergent extension involved in gastrulation; detection of mechanical stimulus involved in sensory perception of sound; determination of left/right symmetry; developmental process; fat cell differentiation; gonad development; heart development; heart looping; hippocampus development; melanosome transport; negative regulation of appetite by leptin-mediated signaling pathway; photoreceptor cell maintenance; pigment granule aggregation in cell center; protein folding; regulation of cilium beat frequency involved in ciliary motility; sensory perception of smell; social behavior; spermatid development; striatum development; animal organ development; developmental process involved in reproduction; and 1 more
Cellular component: centrosome; ciliary basal body; cytoplasm; nucleus; kinociliary basal body; motile cilium; cytosol
Genetic constraint (gnomAD): Loss-of-function variants: 35 observed, 41.72 expected, observed/expected ratio (o/e) 0.84, 90% interval 0.64 to 1.11. The upper end of that interval is the gene's LOEUF score, 1.11, which puts it in group 4 of 6, group 1 being the genes least tolerant of losing a copy. Missense variants: 661 observed, 698.65 expected, observed/expected ratio (o/e) 0.95, 90% interval 0.89 to 1.01. Synonymous variants: 260 observed, 258.4 expected, observed/expected ratio (o/e) 1.01, 90% interval 0.91 to 1.12.
Gene-disease validity (ClinGen):
ClinGen rates the evidence that MKKS causes each of these diseases.
MKKS-related ciliopathy (autosomal recessive): Definitive. Any ciliopathy caused by variants in the MKKS gene.
Homologues: Orthologues: chimpanzee MKKS (99% identical), macaque MKKS (97% identical), dog MKKS (84% identical), rabbit MKKS (82% identical), pig MKKS (81% identical), rat Mkks (78% identical), mouse Mkks (77% identical), guinea pig MKKS (76% identical), tropical clawed frog mkks (51% identical), zebrafish mkks (42% identical). Paralogues in human: CCT3 (19% identical), PIKFYVE (19% identical), CCT4 (17% identical), CCT2 (17% identical), TCP1 (17% identical), CCT6A (17% identical), CCT6B (16% identical), CCT8 (16% identical), CCT7 (16% identical), CCT8L2 (16% identical), CCT5 (15% identical), BBS12 (15% identical), and 1 more.
Diseases named in the same sentence as MKKS in open-access papers:
MKKS is named in the same sentence as 42 diseases in open-access papers, as found by Europe PMC text mining. Sharing a sentence is not in itself a finding about the gene and the disease. The quoted sentences say what the papers report.
Bardet-Biedl syndrome (17 papers, 2010 to 2023). A ciliopathy with multisystem involvement. "Mutations in the MKKS gene have also been shown to cause Bardet–Biedl syndrome which is characterized by pigmentary retinopathy, polydactyly, and renal abnormalities." (PMID 36437957, 2022). "The third gene we identified was MKKS, and the mutations had been detected in patients of Bardet–Biedl syndrome." (PMID 35456484, 2022). "rs6131100 is situated in the intron of SLX4IPA and 20 kbp upstream of MKKS, which is associated with Bardet–Biedl syndrome 6 (OMIM: 605552)." (PMID 28548082, 2017). "One of these four outlier SNPs is located in an intron of the MKKS gene (also known as BBS6), associated with developmental anomaly syndromes in humans: McKusick–Kaufman and Bardet–Biedl syndromes." (PMID 27233669, 2016). "Another gene with mutations exhibiting a Bardet–Biedl syndrome phenotype is MKKS/BBS6." (PMID 36830640, 2023). "MKKS is caused by mutations in the MKKS gene mapped onto chromosome 20p12, however, mutations in the same gene also cause Bardet–Biedl-6 syndrome (BBS-6, OMIM #209900), which, later in childhood, presents with additional retinitis pigmentosa, obesity, mental retardation and renal failure." (PMID 34596737, 2022). "Homozygous mutations in MKKS cause Bardet‐Biedl syndrome, which manifests with polydactyly, obesity, retinitis pigmentosa and intellectual disability or Mc‐Kusick Kaufman syndrome, associated with congenital heart disease, genitourinary abnormalities and polydactyly." (PMID 29271092, 2018). "One gene, MKKS, was named for its association with the developmental disease McKusick-Kaufman Syndrome and was soon after also identified as BBS6 for its association with the Bardet-Biedl Syndrome (BBS), another developmental condition involving cilium-related dysfunction." (PMID 20193073, 2010). "In Group II, MKKS causes the McKusick-Kaufman syndrome characterized by genitourinary malformations (MIM#236700), and BBS10, and BBS12 Bardet-Biedl syndromes (BBS) type 10 (MIM # 615987) and 12 (MIM # 615989)." (PMID 33076433, 2020). "Mutations in the MKKS gene also cause Bardet-Biedl syndrome (BBS), thus MKKS also known as BBS6." (PMID 36918801, 2023).
Obesity (10 papers, 2010 to 2024). Accumulation of substantial excess body fat. "In a previous study of a patient with the c.748G > A (p.G250R) variant in the MKKS gene, the patient presented with obesity and mental delay; however, the phenotype of the patient in this study with the same MKKS variant is different." (PMID 33520300, 2021).
McKusick-Kaufman syndrome (9 papers, 2007 to 2023). McKusick-Kaufman syndrome is a very rare, genetic developmental disorder presenting in the neonatal period characterized by genitourinary malformations, polydactyly, and more rarely, congenital heart disease or gastrointestinal malformations. "The MKKS (McKusick-Kaufman syndrome) gene encodes a 570-amino acid polypeptide with weak but significant similarity to group II chaperonins." (PMID 36918801, 2023). "BBS2 and BBS4 mutations cause BBS, whereas BBS6 (or MKKS) gene defects are associated with McKusick-Kaufman syndrome (abnormalities in finger, heart and genitals) in addition to BBS." (PMID 25650393, 2015). "MKKS and PLCB1genes are associated with McKusick-Kaufman syndrome (OMIM 236700) and Early Infantile Epileptic Encephalopathy-12 (OMIM 613722), respectively, both autosomal recessive disorders." (PMID 22550961, 2012). "Other anomalies of the genetic disorders such as McKusick-Kaufman syndrome (MKKS), includes removal of mutant MKKS protein from the cell by CHIP." (PMID 27757073, 2016). "Mutations in BBS6, for example, are associated not only with BBS, but also with McKusick-Kaufman syndrome (MKKS)." (PMID 28753627, 2017).
ciliopathy (8 papers, 2010 to 2023). A genetic disorder of the cellular cilia or the cilia anchoring structures, the basal bodies, or of ciliary function. "At this point, it is appropriate to mention that MKKS is a monogenic ciliopathy caused by mutations in the MKKS gene leading to postaxial polydactyly, genital malformations (typically hydrometrocolpos in females) and also congenital heart disease." (PMID 28824921, 2017). "Among ciliopathies, BBS represents a special case since as far as we know no other ciliopathy except the related McKusick-Kaufman syndrome (MKKS; MIM#236700) is caused by genetic defects in chaperone genes." (PMID 28824921, 2017).
Retinal dystrophy (4 papers, 2017 to 2025). Retinal dystrophy is an abnormality of the retina associated with a hereditary process. "The MKKS variant in family E was reported with an extremely low frequency from gnomAD v2.1.1 and was also reported as pathogenic for retinal dystrophy (ClinVar ID: VCV000866319; rs759131391) without any evidence from an independent evaluation at the laboratory level." (PMID 37239474, 2023).
retinitis pigmentosa (4 papers, 2017 to 2022). Retinitis pigmentosa (RP) is an inherited retinal dystrophy leading to progressive loss of the photoreceptors and retinal pigment epithelium and resulting in blindness usually after several decades. "Due to the differential phenotypes between MKKS and BBS patients, and the fact that MKKS patients do not display retinitis pigmentosa, we posit that the MKKS disease allele, BBS6H84Y; A242S, may still retain cilia function." (PMID 28753627, 2017).
congenital heart disease (3 papers, 2017 to 2018). A heart disease that is present at birth. "MKKS, the syndrome, is an autosomal, recessive disorder with clinical features including congenital heart defects, female genital anomalies, and postaxial polydactyly." (PMID 28753627, 2017). "Due to the role of the SWI/SNF complex in the heart, we posit that disruption of BBS6-SMARCC1 interaction may contribute to the congenital heart defects observed in MKKS." (PMID 28753627, 2017).
congenital heart malformation (3 papers, 2007 to 2026). A disease that has its basis in the disruption of heart development. "Vaginal atresia is observed in several syndromes, notably Winter syndrome (renal, genital, and middle ear anomalies, OMIM #267400) and McKusick–Kaufman syndrome (hydrometrocolpos, postaxial polydactyly, congenital heart malformations, OMIM #236700), caused by mutations in MKKS on chromosome 20p12." (PMID 41515635, 2026).
hypogonadism (3 papers, 2019 to 2023). A disorder characterized by decreased function of the gonads. "All our MKKS/BBS fetuses were female, but MKKS/BBS in males is possible and can be accompanied by genital malformations or hypogonadism." (PMID 34596737, 2022).
Intellectual disability (3 papers, 2018 to 2023). "The proband, which also presented polydactyly, intellectual disability, renal anomalies, asthma, and seizures, carried the third allele in MKKS (p.(Ala242Ser))." (PMID 35835773, 2022).
Leber congenital amaurosis (2 papers, 2022 to 2025). Leber congenital amaurosis (LCA) is a retinal dystrophy defined by blindness and responses to electrophysiological stimulation (Ganzfeld electroretinogram (ERG)) below threshold, associated with severe visual impairment within the first year of life. "Other studies showed, that the domain deleted in the protein encoded by the Cep290rd16 allele (which, as we know, plays a role in Joubert Syndrome, Meckel–Gruber syndrome, Leber congenital amaurosis and BBS-14) directly interacts with the MKKS protein." (PMID 34596737, 2022).
celiac disease (1 paper, 2016). An autoimmune genetic disorder with an unknown pattern of inheritance that primarily affects the digestive tract. "HSP90AA1, MKKS, EZR, HSPA14, APOB and CAD are proteins that involved in protein networks of celiac disease and have been determined as seeds." (PMID 27895852, 2016).
hypospadias (1 paper, 2022). Hypospadias is the displacement of the urethral meatus on the ventrum of the penis. "Additionally, the MKKS null mouse model also failed to form spermatozoa flagella, which has no clear relevance in hypospadias or CAVD." (PMID 36437957, 2022).
male infertility (1 paper, 2019). The inability of the male to effect fertilization of an ovum after a specified period of unprotected intercourse. "Disruptions of BBS or MKKS genes result in male infertility owing to the failure of flagellum formation in spermatozoa." (PMID 31623114, 2019).
MKKS also shares sentences with these, for which no sentence is quoted: Kidney disease (2 papers); kidney failure (2); Pigmentary retinopathy (2); polydactyly (2); Alström syndrome (1); Anxiety (1); asthma (1); Ataxia (1); autosomal dominant retinitis pigmentosa (1); Brain atrophy (1); cancer (1); Cognitive impairment (1); cone dystrophy (1); congenital hypothyroidism (1); cyst (1); diabetes mellitus (1); Early Infantile Epileptic Encephalopathy-12 (1); genetic disorder (1); Hyperinsulinemia (1); Hypertension (1); Joubert syndrome (1); nonsyndromic deafness (1); Oculo-Auriculo-Vertebral Spectrum (1); renal failure (1); retinal diseases (1); retinopathies (1); syndactyly (1); tumor (1).